IL1B (interleukin 1 beta)
Diseases named in the same sentence as IL1B in open-access papers (continued):
Sharing a sentence is not in itself a finding about the gene and the disease.
atherosclerosis (continued). "Pyroptosis, which is mediated by caspase-1-dependent inflammasome activation and gasdermin proteins, amplifies local and systemic inflammation, accelerating atherosclerosis by releasing inflammatory cytokines such as interleukin (IL)-1β and IL-18." (PMID 39898976, 2025). "Since it also raises many pro-inflammatory cytokines, including interleukin (IL)−6, IL-8, IL-1β, and tumor necrosis factor-alpha, atherosclerosis is hyperactivated by such an inflammatory response." (PMID 41204397, 2025). "A decline in Glo-I activity and an increase in IL-1β levels contribute to the progression of diabetic nephropathy and atherosclerosis." (PMID 39877627, 2025). "The fourth most cited publication, authored by Ridker, provided a pivotal framework for recognizing inflammation, particularly interleukin-1 beta (IL-1β) signaling, as a central driver of atherosclerosis." (PMID 40686723, 2025). "Studies have shown that mutated myeloid cells derived from CHIP clones exhibit a pro-inflammatory phenotype, with enhanced production of interleukin-1β (IL-1β) and interleukin-6 (IL-6), key mediators in the pathogenesis of atherosclerosis and vascular injury." (PMID 41458386, 2025). "IL-1β amplifies local and systemic inflammation and accelerates atherosclerosis, thereby indirectly aggravating nephropathy." (PMID 41154568, 2025). "A double-blind phase-II study supported the use of canakinumab, a monoclonal antibody targeting IL-1β, in the management of inflammation-driven atherosclerosis." (PMID 41272654, 2025). "IL‐1B was involved in the occurrence and development of atherosclerosis, and the expression of IL‐1B around coronary atherosclerosis was positively correlated." (PMID 40824771, 2025). "IL-1β is a crucial cytokine involved in the progression of atherosclerosis, as highlighted by findings from the CANTOS trial." (PMID 40384967, 2025). "The NLRP3 inflammasome/IL-1β-dependent inflammatory response serves as a critical factor and key trigger in exacerbating atherosclerosis (AS), whereas chaperone-mediated autophagy (CMA) recognizes and degrades the NLRP3 inflammasome." (PMID 41282617, 2025). "The mechanistic relationship between IL-1β and atherosclerosis centers on its influence on plaque composition and stability." (PMID 40776916, 2025). "The NLRP3 inflammasome is a crucial regulator of inflammation, myocarditis, and atherosclerosis, and its activation leads to IL-1β secretion, promoting myocardial inflammation and fibrosis." (PMID 40724868, 2025). "This modification was effective in assays related to the early stages of atherosclerosis, indicating IL-1β had more pronounced effects on the monocyte adhesion and migration assays than TNF-α, especially at low concentrations." (PMID 41424804, 2025). "In the context of atherosclerosis, neutrophils have the capacity to prime macrophages for the transcription of IL-1β by releasing NETs." (PMID 38436813, 2024). "To validate the translational relevance of the findings obtained in the mouse model of atherosclerosis in humans, we studied the effect of IL-1β on the expression of TRIM13 and its downstream effectors in human cells." (PMID 38537695, 2024). "Upon stimulation with IL‐1β, a key pro‐inflammatory cytokine involved in atherosclerosis, YAP is K63 ubiquitinated by the E3 ligase TRAF6 at the K252 residue, leading to its protein stabilization and nuclear translocation." (PMID 38778460, 2024). "Previous sections of this paper have highlighted how inflammatory cytokines such as TNF-α, IL-6, and IL-1β contribute to both the RA disease process and atherosclerosis." (PMID 39062180, 2024). "IL-1 family cytokines (mainly IL-1β and IL-18) are crucial to the vascular and systemic inflammation process related to atherosclerosis development." (PMID 39056712, 2024).
atherosclerosis (continued). "Several studies depicted that EVs, in particular exosomes, are involved in the release of inflammasomes and its products, such as NLRP3 and IL-1β in mammalian cells, which enhanced progression of atherosclerosis." (PMID 39770410, 2024). "IL-1β is one of the main cytokines in the inflammatory mechanisms of atherosclerosis, activating and mediating the humoral immune response." (PMID 39232217, 2024). "As flaxseed oil displayed anti-atherosclerosis action against high-fat diet-induced ApoE−/− mice, Intestinimonas was positively correlated with LPS and IL-1β in plasma and with IL-6 and IL-1β in the aorta." (PMID 39403395, 2024). "The NLRP3 inflammasome is required for atherosclerosis, and the by‐products of pyroptosis, IL‐1β and IL‐18, contribute to the occurrence and development of plaques." (PMID 38873710, 2024). "Currently, the hunt to target the inflammatory response in atherosclerosis has accelerated after the positive results of the CANTOS trial, which tested the use of canakinumab (neutralizing anti-IL1β) to treat high-risk atherosclerotic patients with prior MI." (PMID 38381113, 2024). "In the initial stages of atherosclerosis, IL-1β triggers inflammation in the aortic endothelium and promotes the recruitment of inflammatory cells into the blood vessels, leading to their invasion of the intima." (PMID 39796594, 2024). "Second, for some of the atherosclerosis-related functional characterization, we only performed experiments in two donors and only for one IL-1β concentration, which precluded us from formal statistical testing." (PMID 39515317, 2024). "NF-κB and MAPK pathways lead to the transcription of pro-inflammatory cytokines such as TNF-α, IL-1β, and IL-6, amplifying the inflammatory response and contributing to chronic inflammation observed in diseases like atherosclerosis." (PMID 39518939, 2024). "Interleukin-1β (IL-1β) is a pro-inflammatory cytokine that has been identified as both a marker and mediator of inflammation in atherosclerosis." (PMID 38256027, 2024). "In the current study, we demonstrated the feasibility of molecular MRI using an elastin-specific probe to visualize and evaluate an IL-1β targeted anti-inflammatory therapy against atherosclerosis in a murine model." (PMID 39232217, 2024). "In atherosclerosis, the role of IL-1β has been thoroughly studied, but there is evidence that other IL1RAP-related cytokines are implicated in disease progression." (PMID 38563353, 2024). "Taken together, these results suggest that with progressing atherosclerosis, an increase in local IL-1β and decrease in elastin occurs." (PMID 39232217, 2024). "While this observation seems counterintuitive because inflammation resolution is critical to atherosclerosis regression, IL-1β is required for the maintenance of a fibrous cap rich in smooth muscle cells and collagen." (PMID 38433753, 2024). "In the CANTOS trial, canakinumab significantly reduced the rate of recurrent cardiovascular events in patients with atherosclerosis by inhibiting IL-1β." (PMID 39596083, 2024). "It downregulates E-selectin expression and decreases NLPR3 inflammasome activation, suppressing IL-1β and IL-6 release, which are critical inflammatory mechanisms in atherosclerosis." (PMID 39113913, 2024). "Pro-inflammatory cytokines such as TNF-α and IL-1β are well-known pro-atherogenic, and inhibiting these cytokines attenuates atherosclerosis." (PMID 39769009, 2024). "Inflammatory cytokines, such as tumor necrosis factor alpha (TNF-α), interleukin 1 beta (IL-1β), and interleukin 6 (IL-6), are pivotal in the inflammatory response that characterizes atherosclerosis." (PMID 38831182, 2024). "Recent studies, including the CANTOS and VCU-ART trials, have explored the efficacy of IL-1β blockade in various forms of cardiovascular disease including myocardial infarction and atherosclerosis." (PMID 39763850, 2024). "As IL-1β is a key inflammatory mediator in atherosclerosis, we focused our analysis on this cytokine." (PMID 38256027, 2024).
atherosclerosis (continued). "As the CANTOS and COLCOT trials generated promising evidence for the anti-atherogenic effects of IL-1β antibodies and colchicine, the inflammasome has amassed attention as the major driving factor of IL-1β-driven inflammation in atherosclerosis." (PMID 39161593, 2024). "NLRP3 probably has a role in the pathogenesis of atherosclerosis, acting as a proinflammatory molecule that triggers the activation of caspase-1 and pro-IL-1β, pro-IL-18, and the initiation of pyroptosis." (PMID 38929699, 2024). "In experimental atherosclerosis, neutralizing IL1β promotes monocytes to switch to a less inflammatory state, reducing plaque size." (PMID 38975335, 2024). "Our mapping, however, showed IL1B is involved in modulating the IL-17 signaling pathway, lipid and atherosclerosis pathway, and fluid shear stress and atherosclerosis pathway in both breast and lung cancer development." (PMID 38982523, 2024). "CMA function becomes impaired during atherosclerosis progression, leading to increases in NLRP3 inflammasome activation and IL-1β secretion, boosting vascular inflammation and atherosclerosis progression." (PMID 39119608, 2024). "A notable increase in serum IL‐1β, IL‐18, and IL‐6 levels was observed in atherosclerosis mice, and METTL3 knockdown in atherosclerosis mice significantly decreased these inflammatory markers." (PMID 39432244, 2024). "M1 macrophages primarily drive inflammatory responses and disease progression in atherosclerosis through the secretion of pro-inflammatory cytokines (such as IL-1β, IL-6, and TNF-α) and the generation of reactive oxygen species (ROS)." (PMID 39726810, 2024). "As per the study, the overexpression of HDAC3 attenuated the levels of TNF-α and IL-1β in the arterial tissue in a mouse model of atherosclerosis." (PMID 39050859, 2024). "Corroborating the effectivity of mitigating IL-1β activity in human atherosclerosis, depleting IL-1β genetically in Apoe−/− mice has been shown to notably reduce atherosclerosis progression." (PMID 39161593, 2024). "Studies related to the inflammatory storm in atherosclerosis also indicated overexpression of inflammatory cytokines IL-17, IL-1β, and TNF-α, along with elevated expression of Caspase-3, Caspase-9, and Caspase-12." (PMID 39494338, 2024). "The adverse impact of NLRP3 on atherosclerosis primarily hinges on the action of its downstream cytokine IL-1β." (PMID 38248345, 2024). "After feeding low density lipoprotein receptor knockout model mice with a high-fat diet for a period, it was found that their levels of IL-1β and the incidence of atherosclerosis were significantly higher than those of normal mice." (PMID 38317229, 2024). "Decades of research have shown that foam cells in atherosclerosis originate from peripheral blood monocytes, and the secretion of the IL-1β cytokine by macrophage has been proven to be a main driving factor of atherosclerosis pathogenesis." (PMID 39192976, 2024). "The recognition stimulates the activation of AIM2 inflammasome in macrophages, leading to the production of IL-1β and IL-18 in atherosclerosis." (PMID 38774746, 2024). "IL-1β is a key pro-inflammatory cytokine involved in the progression of atherosclerosis and myocardial infarction outcomes." (PMID 39057626, 2024). "A large clinical study, CANTOS, demonstrated the critical role of IL1β in promoting atherosclerosis and the effectiveness of anti-inflammatory therapy in treating it." (PMID 38975335, 2024). "Atherosclerosis (AS) is a chronic inflammatory disease where the release of pro-inflammatory cytokines (e.g. IL1β, IL6, and TNF) promotes its development." (PMID 39044161, 2024).
atherosclerosis (continued). "IL-6 and IL-1β influence various stages of atherosclerosis, from the early recruitment of leukocytes to the development of advanced atherosclerotic lesions." (PMID 39057626, 2024). "Inhibition of AIM2 also reduced IL-1β and IL-18 expression levels in vascular endothelial cells in atherosclerosis-prone mouse model." (PMID 36742336, 2023). "The NLRP3 inflammasome activates caspase-1, acts on the precursor molecules of IL-1β and IL-18, and promotes the maturation and secretion of IL-1β and IL-18 to trigger an inflammatory response and further aggravate atherosclerosis." (PMID 37679676, 2023). "Instead, the combined effect of intermittent hypoxia and IL-1β treatment led to the most pronounced expression of IL-19, IL-24 and IL-32 which are known to be dysregulated in inflammatory disorders, such as atherosclerosis." (PMID 37753073, 2023). "First, it is important to underline that in mice with advanced atherosclerosis, activation of the dsDNA sensing AIM2 inflammasome induced a marked release of the proatherogenic cytokines IL-1β and IL-18." (PMID 36672621, 2023). "Recent research has identified IL-1β and IL-18 as the most important inflammatory cytokines that promote atherosclerosis development." (PMID 37374202, 2023). "Similar results were reported by other studies, in which IL-1β blockade improved cardiac function and atherosclerosis-induced cardiac events." (PMID 37581942, 2023). "A study investigated the role of IL-1β in the progression of atherosclerosis by engineering double-knockout mice (ApoE-/-/IL-1β-/-)." (PMID 36851139, 2023). "Remarkably, we also demonstrate that IL‐1β, a senescence‐associated secretory phenotype (SASP) gene itself and a biomarker for atherosclerosis, induces cellular senescence also by upregulating CUX1 and/or downregulating SATB2 in human ECs." (PMID 36633253, 2023). "In atherosclerotic coronary arteries, IL-1β levels were correlated with disease severity and knocking out IL-1β in atherosclerosis-prone ApoE−/− mice led to attenuation of disease development." (PMID 37251380, 2023). "Animal studies have suggested that Interleukin-1β (IL-1β) is an important cytokine, whose secretion and activation promotes the formation of atherosclerosis and the instability of vascular plaque." (PMID 36791122, 2023). "Of the two, the leaderless cytokine IL-1β has been extensively investigated, and it has been shown to be involved in every stage of atherosclerosis from early lesion formation to progressive late-stage lesions." (PMID 37539090, 2023). "Nevertheless, most studies provide clear evidence identifying the NLRP3 inflammasome and IL-1β as major drivers of atherosclerosis development and progression." (PMID 37239938, 2023). "During atherosclerosis, cholesterol crystals evoke NETs to provide the first priming signal for macrophages, whereas the production of pro-IL-1β provides the second signal for the activation of the NLRP3 inflammasome and the release of mature cytokines." (PMID 36851139, 2023). "Emerging evidence suggests that IL-1β plays a crucial role in the development of atherosclerosis and MI." (PMID 37374202, 2023). "For atherosclerosis, the formation of foam cells was initiated by the release of IL-1β and NLRP3 inflammasomes, which were activated by cholesterol and saturated fatty acids." (PMID 37113481, 2023). "Several reports suggest that IL-1β levels are increased in patients with CVDs such as hypertension and atherosclerosis, where this cytokine participates in the vascular proinflammatory and oxidative responses." (PMID 36937865, 2023). "Once activated, the inflammasome leads to the production of pro-inflammatory cytokines, such as IL-1β and IL-18, which contribute to the progression of atherosclerosis and other cardiovascular conditions." (PMID 37608809, 2023). "In the heart, activation of the NLRP3 inflammasome was related to the enhanced release of interleukin-1β (IL-1β) and the subsequent induction of atherosclerosis and heart failure." (PMID 37242177, 2023).
atherosclerosis (continued). "In a large clinical trial, the Canakinumab Anti-inflammatory Thrombosis Outcome Study (CANTOS), anti-inflammatory therapy against atherosclerosis was found to be effective, and IL-1β played an important role in atherosclerotic plaque generation." (PMID 36769149, 2023). "Gene Expression Omnibus (GEO) validation demonstrated that VEGFA was downregulated, while MMP9 and IL-1β were upregulated in patients with atherosclerosis." (PMID 37880698, 2023). "TNF-α, IL-1β and interferon-γ stimulate SMase activity in the endothelial cells of vessels affected by atherosclerosis, thereby increasing the concentration of ceramides in cells, which probably occurs in adipocytes of AT of the heart and coronary arteries." (PMID 37298446, 2023). "It is conceivable that apoptosis of SMCs resulting from polyploidization causes the release of proinflammatory cytokines and many other factors, including IL-1α and IL-1β, consequently accelerating atherosclerosis in the presence of atherogenic factors." (PMID 36750553, 2023). "TMAO is also associated with disease processes in murine models of atherosclerosis, where it is tied to foam cell formation, NLRP3 inflammasome activation, and generation of the proinflammatory cytokines IL-1β, TNF-α, and IL-6." (PMID 37720032, 2023). "Our results showed that CSE induced the high expression IL-1β and PAPP-A, which plays a crucial role in plaque formation and atherosclerosis, with increased risk of CVD." (PMID 36791122, 2023). "The results were validated using ClueGo + Pedia apps, and the “Fluid shear stress and atherosclerosis” pathway, including the three genes (IL-1β, MMP9, VEGFA), were the target genes in the eight hub genes." (PMID 37880698, 2023). "Both experimental and clinical evidence support that IL‐1β is an important contributor to atherosclerosis and its complications." (PMID 36633253, 2023). "Inthe previous several years, IL-1β and IL-6, two cytokines upstream fromCRP, emerged as key players in atherosclerosis." (PMID 39076864, 2023). "An association between NLRP3 and atherosclerosis pathogenesis has been suggested based on evidence such as a large amount of NLRP3 inflammasome-related components, such as NLRP3, ASC, caspase-1, IL1-β and IL-18 detected in atherosclerotic plaques." (PMID 37336361, 2023). "TNFα and IL-1β are classic proinflammatory cytokines and common inducers of EndMT, playing inflammatory roles during atherosclerosis development." (PMID 38268851, 2023). "This study successfully identified key genes associated with EndMT-related atherosclerosis, such as CD68, TLR2, MYD88, IRF7, STAT1, and IL1B, all of which demonstrate substantial diagnostic potential for detecting atherosclerotic plaques." (PMID 38268851, 2023). "The results suggested that IL-1β plays a significant role in the progression of atherosclerosis by downregulating VCAM-1 and MCP-1 expression in an injured aorta." (PMID 36851139, 2023). "In APN-treated atherosclerosis mice, the inflammatory cytokines IL-1β and IL-18 were significantly decreased." (PMID 37198205, 2023). "In summary, NLRP3 and IL-1β play an important role in the development and progression of atherosclerosis and in this context are primarily activated by cholesterol crystals and extracellular ATP." (PMID 37239938, 2023). "As TNF-α, NF-κB, NLRP3, and IL-1β are crucial genes in the formation of ASC plaques to formulate atherosclerosis, we evaluated their expression in the aorta by Q-PCR." (PMID 37836470, 2023). "The pro‐inflammatory cytokines, including IL‐1β, Interleukin 6 (IL‐6) and tumour necrosis factor‐alpha (TNF‐α), have been regarded as the risk factors in atherosclerosis." (PMID 37905351, 2023).